PPIA (peptidylprolyl isomerase A)
Diseases named in the same sentence as PPIA in open-access papers (continued):
Sharing a sentence is not in itself a finding about the gene and the disease.
ovarian carcinoma (8 papers, 2013 to 2026). A malignant neoplasm originating from the surface ovarian epithelium. "Wang and colleagues used SRM method to detect peptide biomarkers and found that 11 (64.7%) of 17 patients with early ovarian cancer had positive scores of small peptides from peptidyl prolyl cis-trans isomerase A(PPIA), which may be a useful diagnostic marker for ovarian cancer." (PMID 37213272, 2023). "In the subset of ovarian cancer cell lines, the reference genes were PPIA, RPS13 and SDHA, clearly demonstrating the necessity to select genes depending on the research focus." (PMID 23554992, 2013). "Moreover, in the subset of normal and ovarian cancer cell lines, the respective genes were PPIA, RPS13 and SDHA." (PMID 23554992, 2013). "Given that HRPT1 and B2M were expressed differently in the 50 specimens, which suggested that these two genes were not eligible reference genes, the combination of ACTB, RPLP0, PPIA, and TBP was recommended for use in epithelial ovarian cancer studies." (PMID 24776823, 2014). "Recently, it is reported that B2M and 18S RNA are suitable internal reference genes in serum stimulated samples; GUSB and PPIA are believed to serve as internal reference genes in ovarian cancer, while RPL13A is identified to stably transcript in ovarian cancer cells treated with PTX and HCPT." (PMID 28184026, 2017). "From the 12 candidate reference genes we studied, the combination use of ACTB, PPIA, RPLP0, and TBP was identified as a relatively superior normalization strategy, while GAPDH was insufficient for accurate normalization when considering its overexpression in ovarian cancer." (PMID 24776823, 2014).
prostate carcinoma (8 papers, 2007 to 2025). A carcinoma that arises from epithelial cells of the prostate gland. "RNASEK is linked to reduced prostate cancer risk, and PPIA acts as an oncogene in various cancers, negatively correlating with immune checkpoints and immune cell infiltration." (PMID 40340807, 2025). "IPA® projected the association of several proteins’ downregulation, including heat shock protein families α and β (HSPA1A/HSPA1B) and peptidylprolyl isomerase A (PPIA), with prostate cancer apoptosis." (PMID 39598420, 2024). "From the two derived cDNAs, the target gene, encoding PAR1 receptor known to be expressed and regulated in prostate carcinoma and cell lines, was quantified, as well as two dedicated HKGs, namely TBP and PPIA." (PMID 20179706, 2010). "Whereas in prostate cancer and bladder cancer experiments 13 out of 16 and six out of nine genes, respectively, remained as suitable genes for the further calculations with geNorm and NormFinder, only the two genes PPIA and TBP could be considered for these analyses in the current study." (PMID 17559644, 2007).
Alzheimer disease (7 papers, 2012 to 2022). A progressive, neurodegenerative disease characterized by loss of function and death of nerve cells in several areas of the brain leading to loss of cognitive function such as memory and language. "Here, we demonstratethat the most ubiquitous peptidyl prolyl isomerase, peptidyl prolylisomerase A (PPIA), concentrates inside liquid-like droplets formedby the Alzheimer’s disease-associated protein tau, as wellas inside RNA-induced coacervates of a proline–arginine dipeptiderepeat protein." (PMID 36018855, 2022). "Proteomics studies have revealed decreased expression of PPIA in brains of patients with non-Alzheimer’s disease tauopathies, suggesting alterations in PPIA may be associated with the general process of neurodegeneration rather than AD specifically." (PMID 23029078, 2012).
endometrial cancer (7 papers, 2013 to 2024). Primary or metastatic malignant neoplasm involving the endometrium (mucous membrane that lines the endometrial cavity). "Thus, according to the statistical analysis performed on the expression level of the 10 selected reference genes, GUSB, HPRT1 and PPIA were the best candidate for normalization purposes in gene expression studies in endometrial cancer versus normal tissue." (PMID 25473950, 2014). "PSMC4, PUM1 and IPO8 were identified as the best reference genes combination for type 1 endometrial cancer (grades 1, 2 and 3), whereas for type 2 endometrial cancer (serous and carcinosarcoma), UBC, MRPL19, PGK1 and PPIA were the best reference genes combination." (PMID 32439920, 2020).
Hyperglycemia (7 papers, 2014 to 2025). An increased concentration of glucose in the blood. "In response to stimuli such as oxidative stress, inflammation, hypoxia, infection, hyperglycemia and mechanical stretch, expression and transcription of PPIA gene encoding CyPA is induced via Rho-kinase activation." (PMID 35673572, 2022). "Over increasing durations of hyperglycemia exposure, SP1 mRNA levels were evaluated in HRECs and ARPE-19 cells after normalization relative to the mRNA levels of Pumilio homolog 1 (PUM1) and peptidylprolyl isomerase A (PPIA), respectively." (PMID 28706953, 2017).
nasopharyngeal carcinoma (7 papers, 2017 to 2025). A carcinoma arising from the nasopharyngeal epithelium. "In our previous study, five different secretory proteins, including GSN, ADAMTSL4, CALR, PPIA and TXN, have been identified to be associated with the nasopharyngeal carcinoma (NPC) metastasis." (PMID 28107202, 2017).
amyotrophic lateral sclerosis (6 papers, 2021 to 2024). Amyotrophic lateral sclerosis (ALS) is a neurodegenerative disease characterized by progressive muscular paralysis reflecting degeneration of motor neurons in the primary motor cortex, corticospinal tracts, brainstem and spinal cord. "PPIA is a disease modifier that is a translational biomarker for amyotrophic lateral sclerosis and is associated with frontotemporal lobar degeneration." (PMID 35743881, 2022). "We demonstrate that proline/arginine repeat polymers inhibit the folding catalyst activity of PPIA, an abundant molecular chaperone and prolyl isomerase in the brain that is altered in amyotrophic lateral sclerosis." (PMID 34099711, 2021).
esophageal cancer (6 papers, 2013 to 2024). A primary or metastatic malignant neoplasm involving the esophagus. "PPIA had the most stable expression in esophageal cancer tissues (CA) and all esophageal tissues (ALL); RPS18 had the most stable expression in normal esophageal tissues (NO)." (PMID 36467891, 2022).
Obesity (6 papers, 2017 to 2026). Accumulation of substantial excess body fat. "Nonetheless, whether the corresponding proteins translated from more stably expressed genes PPIA, RPLP0, and YWHAZ are appropriate for references in protein studies of obesity, needs to be clarified in the future." (PMID 33330591, 2020).
renal fibrosis (6 papers, 2014 to 2024). A final common manifestation of a wide variety of chronic kidney diseases characterized by glomerulosclerosis and tubulointerstitial fibrosis. "Our data provide evidence of the potential role of PPIA in renal fibrosis." (PMID 32708451, 2020). "Here, we stress the focus on the role of the peptidyl-prolyl cis-trans isomerase A (PPIA), a foldase protein, in renal fibrosis." (PMID 32708451, 2020). "By contrast, studies with the SfA-derived pancyclophilin inhibitor GS-642362, which targets PPIA, PPIB, and PPIF, in the unilateral ureteric obstruction (UUO) mouse model showed inhibition of renal fibrosis by preventing tubular epithelial cell death and neutrophil infiltration." (PMID 38900587, 2024). "Knockdown studies of PPIA in a three-dimensional (3D) cell culture model significantly impaired the secretion and accumulation of the extracellular matrix (ECM), suggesting a positive therapeutic effect on renal fibrosis progression." (PMID 32708451, 2020).
squamous cell carcinoma (6 papers, 2010 to 2024). A carcinoma arising from squamous epithelial cells. "PPIA is a housekeeping gene involved in several cancers including NSCLC, pancreatic adenocarcinomas as well as head, and neck squamous cell carcinomas." (PMID 32592319, 2020).
colon cancer (4 papers, 2010 to 2024). "Two pairs of genes, HPRT1/PPIA and IPO8/PPIA, were identified to be suitable to normalize gene expression data in metastatic and non-metastatic colon cancer patients, according to geNorm and NormFinder respectively." (PMID 21059236, 2010). "We identified two pairs of genes, HPRT1/PPIA and IPO8/PPIA, which may be suitable to normalize gene expression data in studies conducted in metastatic and non-metastatic colon cancer patients." (PMID 21059236, 2010).
esophageal squamous cell carcinoma (4 papers, 2013 to 2024). Esophageal squamous cell carcinoma (ESCC) is a type of esophageal carcinoma (EC) that can affect any part of the esophagus, but is usually located in the upper or middle third. "Some researchers have indicated that overexpression of PPIA is associated with decreased survival in esophageal squamous cell carcinoma and shown it to be an independent prognostic factor." (PMID 35840882, 2022).
liver cancer (4 papers, 2020 to 2023). An epithelial or non-epithelial malignant neoplasm that arises from the liver. "The results revealed that the expression of HSP90AA1, PPIA, SQSTM1, and USP21 was significantly increased in liver cancer tissues compared with normal liver tissues (p < 0.05), which was consistent with the results of the bioinformatics analysis." (PMID 36795724, 2023).
ovarian tumor (4 papers, 2013 to 2026). "In conclusion, for an accurate gene expression assay in ovarian tumor tissues, homogeneous tissues as starting materials and normalization based on multiple validated reference genes, such as PPIA, RPLP0, ACTB, and TBP, are recommended." (PMID 24776823, 2014).
allergic disease (3 papers, 2011 to 2025). An immune response that occurs following re-exposure to an innocuous antigen, and that requires the presence of existing antibodies against that antigen. "The allergenicity prediction from AllerTOP, AllergenFP, and AlgPred indicated that PpiA is non-allergenic, suggesting that it is unlikely to induce allergic reactions, which enhances its suitability for therapeutic applications." (PMID 40333132, 2025). "PPIA knockout mice experience spontaneous TH2-polarized allergic disease and an immune profile akin to AE, although no dermatitis is reported." (PMID 28479159, 2017).
co-infection (3 papers, 2019 to 2025). "Co-infection was accompanied by substantial upregulation of inhibitory pathways, including prostaglandin E2 biosynthesis (PGE2-PTGES3-PTGER2/4), cyclophilin A signaling (PPIA-BSG), and PECAM1-mediated interactions, all known to suppress T-cell activation." (PMID 41394852, 2025).
frontotemporal lobar degeneration (3 papers, 2016 to 2024). "Furthermore, hnRNPA2B1 interacts with another RNA-binding protein, TDP-43, whose presence in protein inclusions is a hallmark of ALS and frontotemporal dementia, and with PPIA, a biomarker of ALS and a key regulator of TDP-43 function." (PMID 27065789, 2016). "Interestingly, several proteins, including VCP and PPIA, which have been associated with ALS and frontotemporal lobar degeneration are among the most commonly identified proteins in EVs." (PMID 27065789, 2016).
lymphoma (3 papers, 2016 to 2023). A malignant (clonal) proliferation of B- lymphocytes or T- lymphocytes which involves the lymph nodes, bone marrow and/or extranodal sites. "Elevated PPIA expression in lymphoma compared with LCL cells is novel and its oncogenic potential is supported by the inhibition of cell growth upon CsA treatment." (PMID 26752561, 2016). "Loss of expression of B2M, and gain of expression of PRDX1 and PPIA was confirmed in the cell lines and primary lymphoma tissue." (PMID 26752561, 2016).
neuroblastoma (3 papers, 2020 to 2024). Neuroblastoma (NB) is the most common solid, extracranial childhood tumor. "Together these findings strongly suggest that ACE2, CD147, PPIA, and PPIB are potential biomarkers and therapeutic targets for neuroblastoma." (PMID 38398114, 2024).
Stroke (3 papers, 2010 to 2019). Sudden impairment of blood flow to a part of the brain due to occlusion or rupture of an artery to the brain. "Corresponding numbers for stroke were 47 proteins with nominal P < 0.05, three of which, apolipoprotein A-II precursor (APOA2), peptidyl-prolyl isomerase A (PPIA), and insulin-like growth factor binding protein 4 (IGFBP4), have a false discovery rate < 0.05." (PMID 20667078, 2010).
acute myeloid leukemia (2 papers, 2021 to 2025). Acute myeloid leukemia (AML) is a group of neoplasms arising from precursor cells committed to the myeloid cell-line differentiation. "Notably, PPIA expression was dramatically up-regulated in almost every solid tumor type compared with normal tissues, except for acute myeloid leukemia." (PMID 40600063, 2025).
colon adenocarcinoma (2 papers, 2008 to 2016). "Normalization against PPIA/RPLP0/SDHA was found optimal for studies involving various colon adenocarcinoma cell lines subjected to manipulations of serum availability." (PMID 27339468, 2016).
cystic kidney disease (2 papers, 2018 to 2020). A congenital or acquired kidney disorder characterized by the presence of renal cysts. "In contrast, in mouse models of renal cystic disease, GAPDH, peptidylprolyl isomerase A and phosphoglycerate kinase have been ranked highest, highlighting the need for model, species and strain specific housekeeping genes." (PMID 32437461, 2020). "GAPDH, PPIA and PGK1 were also recommended as reference transcripts in studies about mice with cystic kidney disease." (PMID 29534701, 2018).
inflammatory bowel disease (2 papers, 2023 to 2024). A spectrum of small and large bowel inflammatory diseases of unknown etiology. "PPIA promotes CRC by regulating the inflammatory response of inflammatory bowel disease." (PMID 37124724, 2023).
lung squamous cell carcinoma (2 papers, 2021 to 2022). "In contrast, in lung squamous cell carcinoma, the expression of PPIA further increased at cancer stage 4, whereas the expression of BSG was similar at all cancer stages." (PMID 36012604, 2022).
tuberculosis (2 papers, 2017 to 2025). A chronic, recurrent infection caused by the bacterium Mycobacterium tuberculosis. "Since PpiA is known to be expressed late in the infection cycle, the pro-inflammatory cytokines induced by PpiA is likely associated with immunopathological responses in tuberculosis leading to necrosis and cachexy that aid in disease progression." (PMID 28261567, 2017). "Targeting PpiA could not only contribute to a better understanding of Mtb’s molecular mechanisms but also open avenues for developing more effective diagnostic and therapeutic strategies against tuberculosis." (PMID 40333132, 2025). "Our results implicate M. tb PpiA as a stimulator of pro-inflammatory cytokines thereby pointing to its vital role in the inflammatory pathology of tuberculosis." (PMID 28261567, 2017).
ulcerative colitis (2 papers, 2021 to 2025). An inflammatory bowel disease involving the mucosal surface of the large intestine and rectum. "This study describes a novel mouse model of ulcerative colitis that combines a genetic modification approach, specifically, the overexpression of the human PPIA gene in the vascular endothelium, and a chemical approach: administration of a low dose of DSS." (PMID 41465494, 2025).
cholesteatoma (1 paper, 2020). A pathologic process characterized by the proliferation of keratinizing squamous epithelium resulting in the accumulation of keratin and cells in the middle ear and/or mastoid. "However, the differences in expression levels between tissue groups for each gene were small; only the expression of HPRT1, PGK1, PPIA, ATP5B and YWHAZ was significantly higher in healthy MA compared to the mucosa from the middle ear in cholesteatoma patients." (PMID 32915926, 2020).
clear cell renal cell carcinoma (1 paper, 2007). "Our study demonstrated the suitability of the two housekeeping genes PPIA and TBP as endogenous reference genes when comparing malignant tissue samples with adjacent normal tissue samples from clear cell renal cell carcinoma." (PMID 17559644, 2007).
colitis (1 paper, 2025). Inflammation of the colon. "Hence, elevated blood levels of CypA in PPIA×Tie-Cre mice could trigger activation of immune effectors and promote systemic accumulation of pro-inflammatory factors, thus creating a primed state in these mice and increasing their susceptibility to colitis." (PMID 41465494, 2025).
developmental delay (1 paper, 2017). "PPIA, IGFBP-3, GCK, GRB10, and H2AFV have HI <10% and that patient’s phenotype includes global developmental delay, tall stature, macrocephaly, depressed nasal bridge, pectus excavatum, and hypospadias." (PMID 28387648, 2017).
endometrial tumors (1 paper, 2014). "In that investigation 38 endometrial tumors and associated normal specimens were examined using qPCR, followed by GeNorm and NormFinder algorithms, that found HPRT1, POLR2A and PPIA as the most stable reference genes." (PMID 25473950, 2014).
fibrosarcoma (1 paper, 2020). A malignant mesenchymal fibroblastic neoplasm affecting the soft tissue and bone. "Real-time PCR analysis showed that silencing SAPCD2 decreased expression levels of multiple downstream genes of the Hippo pathway, including CTGF, CYR61, SOX9, HOXA1, RPL13A, and PPIA in fibrosarcoma cells." (PMID 33384953, 2020).
keratitis (1 paper, 2010). A corneal disease that is characterized by inflammation of the cornea. "Namely, geNorm proposed PPIA and HRPT1 and PPIA and RPL5 pairs for chemical burn-induced CorNV in Balb/c and C57BL/6 mice, respectively, while UBC and HPRT1 and UBC and LDHA were best for Candida and Aspergillus induced keratitis in Balb/c mice, respectively." (PMID 20596249, 2010).
laryngeal carcinoma (1 paper, 2016). Carcinoma that arises from the laryngeal epithelium. "In the tissue group, PPIA and RPL29 had the lowest M-values, followed by HPRT1, which suggests that these same genes are the most stable internal reference genes for the study of human laryngeal cancer tissues." (PMID 27957397, 2016).
malignant glioma (1 paper, 2024). A grade III or grade IV glioma arising from the central nervous system. "The interaction between malignant glioma cells and CAFs was mainly conducted through PTN-NCL and PPIA-BSG signaling pathways." (PMID 39033204, 2024).
meningioma (1 paper, 2011). A generally slow growing tumor attached to the dura mater. "Eight highest ranked reference genes (CASC3, EIF2B1, IPO8, MRPL19, PGK1, POP4, PPIA, and RPL37A) plus GAPDH and ACTB were then analyzed in 35 meningiomas, arachnoidea, dura mater and normal brain." (PMID 21806841, 2011).
multinodular goiter (1 paper, 2019). Nodular goiter characterized by more than one discrete tissue mass. "The expression characteristics of 12 candidate reference genes (GAPDH, ACTB, HPRT1, TBP, B2M, PPIA, 18SrRNA, HMBS, GUSB, PGK1, RPLP0, and PGM1) were assessed by qRT-PCR in 45 thyroid tissue samples (15 papillary thyroid carcinoma, 15 paired normal tissues and 15 multinodular goiters)." (PMID 31645594, 2019).
nasal polyps (1 paper, 2017). "The PPIA enzyme has been implicated in a wide range of inflammatory and apoptosis pathways, while ADH7 is a hormone that participates in cellular differentiation and could play a crucial role in formation of nasal polyps." (PMID 29270391, 2017).
Ogden syndrome (1 paper, 2025). Ogden syndrome is a rare, genetic progeroid syndrome characterized by a variable phenotype including postnatal growth delay, severe global developmental delay, hypotonia, non-specific dysmorphic facies with aged appearance and cryptorchidism, as well as cardiac arrthymias and skeletal anomalies. "Combined analyses of Ogden syndrome cellular models and HeLa cancer models identified a subset of common N-terminally acetylated proteins, including GCN1, ELOA, PPIA, RPL13A, RPP30, and SAE1." (PMID 40558489, 2025).